NOTCH2 (notch receptor 2)
Diseases named in the same sentence as NOTCH2 in open-access papers (continued):
Sharing a sentence is not in itself a finding about the gene and the disease.
glioma (continued). "Although miR-107 expression is down-regulated in glioma tissues and cell lines, its overexpression can directly target and regulate Notch2, which inhibits the migratory and invasive capacity of glioma cells, a known target for Tenascin-C and COX-2 trans-activation." (PMID 36479040, 2022). "Notch2 is known to be a significant prognostic marker in glioma independent of other mutation patterns." (PMID 36643842, 2021). "The outcomes showed that TSN could inhibit glioma progression property and induce apoptosis via upregulating the expression of miR-608 and downregulating the expression of miR-608 targets, Notch1 and Notch2, in glioma." (PMID 35140606, 2021). "The data reported here implied that Notch2 could play a predominant role in GBM multiplication, and the inhibition of Notch2 caused by NAC might contribute to glioma therapy." (PMID 30606241, 2019). "Notch1 and Notch2 are highly expressed in glioma cell lines as well as primary human gliomas." (PMID 30606241, 2019). "Studies have shown that Notch2 is regulated by miR-107 in glioma." (PMID 30470250, 2018). "Furthermore, a recent report compared the role of the Notch paralogs Notch1 and Notch2, which displayed opposing effects on the propagation of glioma cells." (PMID 25601901, 2014). "However, it has been reported that Notch2 expression varies in different glioma cells, such as astrocytoma and medulloblastoma cells." (PMID 25323114, 2014). "This indicates that Notch2 may act as an oncogene or tumor suppressor protein, depending on the type of glioma." (PMID 25323114, 2014). "Additionally, expression of the constitutively active intracellular domains of Notch1 or Notch2 is protective while knockdown of Notch1 or Notch2 is sensitizing for glioma TSC exposed to radiation." (PMID 24212632, 2011). "The Notch signaling pathway comprises four receptors: Notch1, which may function as either a tumor suppressor or oncogene; Notch2, considered a prognostic marker in glioma; Notch3, which promotes glioma cell proliferation; and Notch4, associated with increased tumor aggressiveness." (PMID 40942013, 2025). "This hypothesis is supported by an in vivo CRISPR screen that identified Notch1 among potential tumor suppressors in glioma, and is further in line with the occurrence of NOTCH1, NOTCH2, and RBPJ inactivating mutations and/or reduced Notch signaling activity in human glioma subtypes." (PMID 36358826, 2022). "However, we have recently shown that glioma cells lacking Notch1 are more aggressive than glioma cells lacking Notch2, despite efficient deletion of both Notch1 and Notch2 floxed alleles." (PMID 36358826, 2022). "Although multi-gene combination therapy is far more effective than selective gene therapy, it still cannot completely inhibit glioma growth, and further studies are suggested.>In another study, researchers used Notch1 siRNA to reduce Notch1 function and increase Plasmid-induced Notch2 expression." (PMID 36643842, 2021). "In glioma, γ-secretase inhibitors (GSIs) that suppress Notch pathway enhanced the sensitivity of glioma stem cells to radiation at clinically relevant doses; knockdown of Notch1 or Notch2 sensitized glioma stem cells to radiation and impaired xenograft tumor formation." (PMID 28038467, 2017). "Besides Notch3, Notch1 and Notch2 also protected glioma stem-like cells against radiation." (PMID 26273424, 2015). "Consequently, it is clear that Notch2 expression levels vary depending on the type of glioma." (PMID 25323114, 2014). "Consequently, it was hypothesized that Notch2 may have a dual effect on the proliferation of glioma cells." (PMID 25323114, 2014). "Seven ferroptosis-related hub genes, namely SLC39A14, WWTR1, STEAP3, NOTCH2, IREB2, HIF1A, and FANCD2, were identified, all of which were highly expressed in glioma." (PMID 37978473, 2023).
glioma (continued). "Corresponding with a previous report, Notch inhibition via short-hairpin RNA (shRNA) targeting Notch2 downregulates MCM2 and p21 expression, hence inducing cell cycle arrest in U87 human glioma cells." (PMID 36012128, 2022). "Thus, Notch2 may be a key therapeutic target for the treatment of glioma." (PMID 25323114, 2014). "Prior reports have shown that miR-34a is downregulated in GBM compared to normal brain, and that it inhibits cell proliferation, survival, and invasion in adherent glioma cell lines by targeting MET, NOTCH1, NOTCH2, and CDK6." (PMID 22479456, 2012). "Here, we demonstrate that the combination of IL-1β and TGF-β can promote self-renewal and oncogenic capability of glioma cells by inducing expression of stemness factor genes Bmi-1, LIF and Notch-2." (PMID 22330721, 2012). "LINC01410 up-regulated NOTCH2 and activated NOTCH signaling by miR-506-3p sponging in glioma cells." (PMID 37051101, 2023). "In glioma, miR-34a suppresses cell cycle progression and proliferation of glioma cells through direct inhibition of the expression of MET receptor tyrosine kinases (c-MET RTK), Notch-1, Notch-2, cyclin-dependent kinase 6 (CDK6), cyclin 1 (CCND1), and silent information regulator 1 (SIRT1)." (PMID 35922753, 2022). "Considering both TRPM7 and Notch signaling function as oncogenes in glioma formation, it is not surprising to see that U87MG cells, transfected with M7-wt, express increased levels of Notch1 NICD, Notch2 NICD, and Notch3 NICD." (PMID 33381038, 2020). "This analysis revealed no major changes in NOTCH1, NOTCH2 and NOTCH4 transcript levels in our glioma population." (PMID 24143218, 2013).
gastric cancer (40 papers, 2012 to 2025). A primary or metastatic malignant neoplasm involving the stomach. "Conversely, other evidence indicates that high NOTCH2 expression is associated with increased gastric cancer risk, advanced TNM stage, and poor outcomes." (PMID 41200204, 2025). "CARM1-mediated transcriptional activation of the NOTCH2 signaling pathway is linked to NOTCH2 methylation in gastric cancer progression." (PMID 37536629, 2023). "Notch 2′s high mRNA expression was only associated with better OS in 5-FU based adjuvant gastric cancer patients, HR 0.61 (0.43–0.87), p = 0.0059." (PMID 27363496, 2016). "Notch 2′s high mRNA expression was associated with worsen OS in grade I gastric cancer patients, HR 10.5 (1.4–78.81), p = 0.0046." (PMID 27363496, 2016). "The Notch receptor family encompasses four members, and NOTCH1 and NOTCH2 have been implicated to enhance gastric cancer progression." (PMID 22970250, 2012). "Studies have shown that Notch2 expression is closely associated with patient prognosis and tumor cell resistance, and our analysis further revealed that high Notch2 expression is linked to poor prognosis in gastric cancer patients." (PMID 40393971, 2025). "Interestingly, Notch 2′s high mRNA expression is only associated with better OS in 5-FU based adjuvant gastric cancer patients." (PMID 27363496, 2016). "In gastric cancer, some studies have reported that strong cytoplasmic or nuclear NOTCH2 expression correlates with favorable prognosis, suggesting a tumor-suppressive role." (PMID 41200204, 2025). "We further identified multiple arginine methylation sites on NUSAP1 and demonstrated that PRMT1-mediated R422me2 modification facilitates its interaction with Notch2, stabilizing Notch2 protein expression and promoting 5-FU resistance in gastric cancer cells." (PMID 40393971, 2025). "In conclusion, our study identifies a novel mechanism by which PRMT1-mediated methylation of NUSAP1 promotes 5-FU resistance in gastric cancer by stabilizing Notch2." (PMID 40393971, 2025). "Gastric cancer patients exhibiting high NOTCH2 or HEY1 expression had significantly poorer prognosis than those with lower levels, respectively." (PMID 39524442, 2024). "Overall, these findings suggested a potential mechanism that MFAP5 promoted gastric cancer progression through the MFAP5/Notch2/HEY1 signaling axis." (PMID 39524442, 2024). "SUMOylation inhibition of SP1 increases its expression level, which promotes the expression of LncRNA SNHG17 and alters the miR-23b-3p/Notch2 pathway, thus promoting the occurrence and development of gastric cancer." (PMID 37777749, 2023). "DLEU2 promotes gastric cancer progression via serving as ceRNA for miR-23b-3p enhancing Notch2 expression." (PMID 36229883, 2022). "The current understanding is that the Notch signal pathway, especially Notch1/Notch2 signaling, has an oncogenic effect on stomach cancer." (PMID 35382168, 2022). "Studies have shown that activation of Notch1 and Notch2 in gastric cancer tissues aggravates gastric cancer progression." (PMID 34234838, 2021). "Compared to GES-1 cells, Notch1 RNA and protein expression was higher in the various gastric cancer cells, whereas Notch2 expression was variable." (PMID 32117763, 2020). "MIR22HG suppressed gastric cancer progression through attenuating NOTCH2 signaling MIR22HG repressed cell proliferation, migration and invasion in CCA by negatively regulating the Wnt/β-catenin signaling pathway." (PMID 31291201, 2019). "Several studies have shown that Notch 1 and Notch 2 expressions were detected in cancerous tissues when compared with normal mucosa, and they were correlated with gastric cancer formation." (PMID 29849934, 2018). "In neoadjuvant-treated gastric cancer, the expression profiling of stem cell-related genes indicated that Notch2, GSK3β, and β-catenin gene signatures predict survival." (PMID 30470250, 2018).
gastric cancer (continued). "For example, miR-34 family inhibited Notch1 and Notch2 levels in glioma and gastric cancer cells and suppressed self-renewal of pancreatic cancer stem cells through targeting Notch1 and Notch2 receptors." (PMID 27191259, 2016). "In this report, Notch2′s high mRNA expression was found to be significantly correlated to worsen OS for all gastric cancer patients, as well as in intestinal type cancer patients and in diffuse type cancer patients." (PMID 27363496, 2016). "Our results suggest that Notch2 pathway and miR-23b interplay in a reciprocal regulation loop in gastric cancer cells and this axis plays an important role in gastric carcinogenesis." (PMID 26041881, 2015). "In this study, we first aimed to clarify the role of NOTCH1 and NOTCH2 protein expression in gastric carcinomas relative to prognosis and to the clinico-pathological characteristics of patients not treated by chemotherapy." (PMID 25954607, 2015). "Furthermore, miR-196a, which is upregulated in gastric cancer, downregulates Notch2 expression, inhibiting the proliferation and invasive potential of gastric cancer cells." (PMID 40621472, 2025). "A recent study demonstrated that Penicilazaphilone C could induce apoptosis in gastric cancer by blocking the notch receptors, Notch1 and Notch2." (PMID 36768307, 2023). "MIR22HG suppresses Notch2 signaling, inhibiting progression of gastric cancer." (PMID 36229883, 2022). "Expression of Notch1 and Notch2 decreases after gastric cancer resection." (PMID 34234838, 2021). "Notch2 activation was observed in 10.0% (1 of 10) of noncancerous endoscopic mucosa, 71.4% (30 of 42) in premalignant lesions, and 97.3% (72 of 74) in gastric cancer tissues, demonstrating a correlation of Notch2 expression with both intestinal and diffuse gastric cancer formation." (PMID 27363496, 2016). "Their results support that Notch2 expression with early tumor stages suggest that Notch2 may act as a tumor suppressor in gastric cancer." (PMID 27363496, 2016). "In gastric cancer cells, Notch1 and Notch2 pathways have been shown to promote tumorigenesis." (PMID 27191259, 2016). "Notch2′ high mRNA expression was found to be significantly correlated to worsen OS for all gastric cancer patients, HR 1.58 (1.31–1.89), p = 6.5e-07, as well as in intestinal type cancer patients, HR 2.36 (1.72–3.25), p = 5.3e-08, and in diffuse type cancer patients, HR 1.62 (1.15–2.28), p = 0.0051." (PMID 27363496, 2016). "Additionally, miR-34 family down-regulates Notch1 and Notch2 levels in gastric cancer cells and also inhibits self-renewal of pancreatic cancer stem cells via directly modulating Notch1 and Notch2 receptors." (PMID 26041881, 2015). "Because c-Myc and E2F1 activate each other's transcription, we checked whether Notch2 pathway suppresses miR-23b expression through E2F1 in gastric cancer cells." (PMID 26041881, 2015). "It was found that Notch2 pathway and Ets1 contribute to gastric cancer progression and metastasis." (PMID 26041881, 2015). "Furthermore, miR-23b diminished the xenografted tumor growth and lung metastasis of SC-M1 gastric cancer cells through Notch2 pathway." (PMID 26041881, 2015). "Furthermore, in cisplatin-resistant gastric cancer tissues, it was found that low-SUMOylation of SP1 increased the expression of SP1 in gastric cancer tissues, and the increased SP1 promoted drug resistance of gastric cancer cells through the SNHG17/miR-23b-3p/Notch2 axis." (PMID 37777749, 2023). "Studies have shown that a high expression of MIR22HG is positively correlated with the OS of patients with hepatocellular carcinoma following hepatectomy, and a high expression of MIR22HG could suppress gastric cancer progression by attenuating NOTCH2 signalling." (PMID 32964046, 2020). "In this study, we aimed to clarify the clinicopathological significance and the prognostic and predictive value of NOTCH1 and NOTCH2 expression in gastric cancer (GC)." (PMID 25954607, 2015).
gastric cancer (continued). "In some cancer types, NOTCH2 has shown a significant relevance to aggressiveness and carcinogenesis instead of NOTCH1, such as gastric cancer, hepatic carcinoma, pancreatic cancer, and bladder cancer." (PMID 40387567, 2025). "A meta-analysis of 15 studies containing 1547 gastric cancer cases and 450 controls from the MEDLINE, EMBASE, and Chinese National Knowledge Infrastructure (CNKI) databases revealed that the expression of Notch1 and Notch2 was significantly higher in tumor tissues of GC compared to normal tissues." (PMID 36768307, 2023). "In gastric cancer (GC) patients, both tumor tissue and peripheral blood showed significantly higher expression of Notch receptor (NOTCH1, NOTCH2) mRNA than normal human gastric tissue, and they also had higher proportions of Treg cells and Th17 cells." (PMID 37131214, 2023). "In many previous studies, gene signatures were ever identified when analyzing expressions in residual gastric cancer cells after neoadjuvant chemotherapy, composing of GSK3B, the β-catenin gene CTNNB1, NOTCH2 and many other genes." (PMID 29088749, 2017). "Increased activation of Notch signaling observed in skeletal muscle of mdx;Mmp9+/− mice is in agreement with a previous report of a direct negative regulation between Notch2 and MMP-9 in human gastric carcinoma cells." (PMID 23977226, 2013). "Our study analysing the expression of CSC related genes in residual gastric cancer cells after neoadjuvant chemotherapy identified a gene signature with a high prognostic impact composed of GSK3B, the β-catenin gene CTNNB1 and NOTCH2." (PMID 22970250, 2012). "The co-culture of macrophages and stomach-cancer cells MKN45 and BGC823 could enhance cell proliferation accompanied by the activation of Notch1/Notch2 signaling and upregulation of DLL3." (PMID 35382168, 2022). "However, there is no report about the prognostic significance of Notch2 mRNA expression in gastric cancer." (PMID 27363496, 2016). "In gastric cancer (GC), NOTCH1 and NOTCH2 are believed to contribute to tumor progression." (PMID 25954607, 2015).
pancreatic cancer (33 papers, 2009 to 2026). "ROC analysis demonstrated that NOTCH2 had strong diagnostic performance for pancreatic cancer, with an AUC of 0.829 in the TCGA-PAAD cohort and 0.823 in the GSE15471 cohort." (PMID 41200204, 2025). "Mutations that activate Notch receptors (NOTCH1 and NOTCH2) have been detected in a subset of pancreatic cancer cases, leading to ligand-independent activation of Notch signaling." (PMID 39087024, 2024). "Ectopic expression of miR-34a, as tumor suppressive miR, caused downregulation of Bcl-2, Notch1, and Notch2 and also inhibition of cell proliferation and invasion, induction of apoptosis and cell cycle arrest in pancreatic cancer cells." (PMID 32489562, 2020). "In vitro functional assays confirmed that knockdown of NOTCH2 inhibited the proliferation and migration of pancreatic cancer cells." (PMID 41200204, 2025). "We identified NOTCH2 as a key biomarker, showing upregulated expression in pancreatic cancer tissues and cell lines, which correlated with poor prognosis and increased infiltration of M2 macrophages." (PMID 41200204, 2025). "To further elucidate the role of NOTCH2 in the progression of pancreatic cancer, we performed a series of in vitro functional assays." (PMID 41200204, 2025). "Taken together, NOTCH2 plays a complex yet critical pro-tumorigenic role in the pathophysiological progression of pancreatic cancer." (PMID 41200204, 2025). "Pancreatic cancer patients were stratified into high- and low-NOTCH2 expression groups based on the median expression level." (PMID 41200204, 2025). "Collectively, these findings indicate that knockdown of NOTCH2 suppresses the proliferation and migration of pancreatic cancer cells." (PMID 41200204, 2025). "In this study, we established a robust prognostic signature for pancreatic cancer and identified NOTCH2 as a potential prognostic biomarker." (PMID 41200204, 2025). "During the early stages of pancreatic cancer, activation of NOTCH2 signaling led to abnormal MYC upregulation, which drove proliferation and malignant transformation of precancerous lesions." (PMID 41200204, 2025). "This study demonstrated the upregulated expression of NOTCH2 in pancreatic cancer tissues and its correlation with adverse clinical outcomes." (PMID 41200204, 2025). "Immunohistochemical staining from the HPA database confirmed higher NOTCH2 protein expression in pancreatic cancer tissue, with predominant nuclear localization." (PMID 41200204, 2025). "Functionally, knockdown of NOTCH2 in vitro inhibited the proliferation and migration of pancreatic cancer cells while increasing both intracellular iron concentration and lipid peroxidation levels." (PMID 41200204, 2025). "During the development of pancreatic cancer, NOTCH2 exhibits a dynamic expression pattern and contradictory roles." (PMID 41200204, 2025). "Our study establishes a ferroptosis-related signature for prognostic prediction in pancreatic cancer and identifies NOTCH2 as a critical prognostic biomarker." (PMID 41200204, 2025). "Researchers found Notch-2 activation in pancreatic cancer cells, which experienced the EMT process and showed resistance against gemcitabine." (PMID 39941895, 2025). "To address this limitation, we integrated transcriptomic data from the TCGA and GTEx databases to compare NOTCH2 expression between pancreatic tumor and normal tissue." (PMID 41200204, 2025). "Finally, results from iron staining and oxidative stress analysis revealed that knockdown of NOTCH2 was associated with iron accumulation and increased lipid peroxidation, suggesting that NOTCH2 may contribute to pancreatic cancer progression by modulating ferroptosis and redox homeostasis." (PMID 41200204, 2025). "The depletion of Notch-2 or midkine suppresses EMT in pancreatic cancer cells through Notch-2-mediated mechanisms." (PMID 39087024, 2024). "Notch-2 or midkine (a downstream target of Notch-2) knockdown induces EMT inhibition in pancreatic cancer cells." (PMID 33918146, 2021).